BRAF (B-Raf proto-oncogene, serine/threonine kinase)
Diseases named in the same sentence as BRAF in open-access papers (continued):
Sharing a sentence is not in itself a finding about the gene and the disease.
melanoma (continued). "The data generated in this publication have possible implications beyond melanoma patients following the tumor-type agnostic approval of dabrafenib and trametinib for solid tumors harboring BRAF V600E activating mutations in 2022." (PMID 39207855, 2024). "The determination of the BRAF codon 600 mutation status is essential in the treatment of patients with advanced melanoma." (PMID 39125519, 2024). "We demonstrate that eIF4F is essential for maintaining optimal ERK signaling intensity in treatment-naïve melanoma cells harboring BRAF or NRAS mutations." (PMID 39436655, 2024). "It showed responses in 15% of 68 patients, with responses seen in 50% of patients with MAPK inhibitor-naive BRAF-mutated melanoma." (PMID 38203795, 2024). "Altogether these results show that miR-579-3p and MITF expression levels are co-regulated in BRAF mutated melanoma and that this co-regulation is linked to activation of BRAF-MAPK signaling." (PMID 38472212, 2024). "The BRAF is proto-oncogene and has been found to be mutated in a variety of cancers, including non-small cell lung cancer, colorectal cancer, and melanoma to mediate the oncogenetic phenotype." (PMID 38329437, 2024). "The identification and characterization of BRAF mutations led to the development of specific drugs that radically changed the therapeutic approach to melanoma." (PMID 38201012, 2024). "In melanoma patients harboring the BRAF V600E mutation, combining BRAF and MEK inhibitors significantly enhances treatment efficacy." (PMID 39113705, 2024). "Four melanomas associated with benign nevi harbored BRAF V600 mutations akin to their matched benign counterparts." (PMID 38396984, 2024). "BRAF mutations have been identified in diverse tumors ranging from melanoma to hematologic malignancies." (PMID 38814411, 2024). "Our research group has provided robust evidence as to the involvement of a set of microRNAs in the development of resistance to target therapy in BRAF-mutated melanomas." (PMID 38472212, 2024). "The genomic profiling of melanoma tumors revealed several recurrent mutations involved in their pathogenesis and evolution, such as BRAF, NRAS, and KIT, contributing to these tumors’ genomic subtyping." (PMID 38396984, 2024). "In summary, our findings revealed that the up-regulation of TMEM16A is correlated with the constitutive activation of the MEK/ERK and AKT signaling pathways in BRAF-mutated malignant melanoma cells, resulting in a poor prognosis for patients with this tumor." (PMID 39070550, 2024). "In keeping with these findings, cases with BRAF mutations in our cohort trended toward being younger, and 90% of the BRAF-mutated melanomas were of the superficial spreading subtype." (PMID 38183457, 2024). "Mitogen-activated protein kinase inhibitors (MAPKi) were the first line drugs for advanced melanoma patients with BRAF mutation." (PMID 38822350, 2024). "Studies of melanoma cell lines that express BRAF mutation indicate a mechanism related to EGFR overexpression and activation of the MAPK and PI3K-AKT pathways after drug administration." (PMID 38396984, 2024). "A 38‐year‐old, white British female with a history of Addison's disease had localised BRAF V600‐mutated melanoma diagnosed 6 years previously." (PMID 39157612, 2024). "BRAF is a biomarker commonly evaluated in the tumor vaccine trials previously discussed, making BRAF mutations a prominent topic in melanoma." (PMID 39682188, 2024). "Acral melanomas display a profile of driver mutations similar to that observed in cutaneous melanomas, with BRAF being the most frequently mutated, followed by NRAS and NF1 mutations." (PMID 39727691, 2024). "Immunotherapy and targeted therapy are currently two alternative backbones in the therapy of BRAF‐mutated malignant melanoma." (PMID 38491825, 2024). "About 40–60% of melanomas exhibit activating BRAF mutations, with V600E mutations accounting for 70–90% of these cases." (PMID 38891988, 2024).
melanoma (continued). "The approach to treating BRAF-mutated melanoma still lacks effectiveness despite the advancement in prognosis for advanced melanoma due to immune checkpoint inhibition." (PMID 39582535, 2024). "Only a minor fraction of acral melanomas bear point mutations in BRAF and TERT, which are common in sun-exposed melanomas." (PMID 39034322, 2024). "In this study, through database analysis and clinical tissue studies, we demonstrated that the expression of CTHRC1 was significantly associated with the BRAF(V600E) mutation in colon cancer, thyroid cancer, and melanoma." (PMID 39052013, 2024). "The aim of our investigation was to determine and compare the frequency of BRAF V600 gene mutations in dysplastic nevi and melanoma in situ, as research on this topic is scarce and inconclusive." (PMID 39200941, 2024). "Here, we show that systemic BRAF/MEK inhibition synergizes with intratumoral RIG-I activation, inducing an immunogenic cell death in BRAF-mutated human and murine melanoma cells." (PMID 39165562, 2024). "To assess the role of CDK12 in melanoma cells, we treated five BRAF-mutated melanoma cell lines (Colo829, A375, WM164, WM983A, WM983B) with increasing concentrations of SR-4835, a recently described ATP-competitive inhibitor of CDK12 and CDK13." (PMID 38104154, 2023). "The BRAF mutation rate in all cancers is about 7%, but the rate varies, being about 66% in melanoma and 10%–25% in CRC." (PMID 36959802, 2023). "This is important because oncogene (i.e., KRAS, BRAF or MYC)-induced Nrf2 transcription activity associates to increases in melanoma growth and pharmacological resistance." (PMID 36766760, 2023). "In melanoma, many of the tumors which are BRAF wild-type carry activating mutations of NRAS, which encodes another component of the MAPK pathway positioned above RAF in the signaling cascade." (PMID 37219686, 2023). "There are several targeted therapies that have been developed to specifically target MAPK pathway mutations in melanoma, including BRAF inhibitors and MEK inhibitors." (PMID 37504268, 2023). "We previously demonstrated in BRAF-mutated patients an association between high levels of Nox4 and metastasis occurring at least 1 year after melanoma diagnosis." (PMID 37189846, 2023). "Approximately 50% of melanomas contain activating point mutations in the BRAF gene, with the most common V600E mutation." (PMID 36704723, 2023). "The tumor-driving BRAF(V600E) mutation is present in approximately 50% of human melanomas and represents a major therapeutic target." (PMID 37445731, 2023). "For patients with advanced melanoma with targetable BRAF mutations, treatment with BRAF/MEK inhibitors and ICIs are both potential front-line treatment options." (PMID 36831449, 2023). "The BRAFV600E mutation is the most commonly observed in patients, represents more than 90% of BRAF mutations in melanoma, and can be detected early during melanoma development." (PMID 36766760, 2023). "Drug-resistant cells showed a rise in ROS after acquiring resistance, suggesting that resistance to the BRAF inhibitor in melanoma cells is linked to oxidative stress." (PMID 37189846, 2023). "PI3K-Akt signalling is constitutively activated by mutant NRAS, as well as the PTEN tumour suppressor which is found to be effected by loss of function mutations in approximately 20% of BRAF-mutant melanomas, resulting in Akt activation." (PMID 37181747, 2023). "Regarding the prevalent melanoma-related mutated genes BRAF, NRAS and NF1, 38 known oncogenic mutations were found in all 46 melanoma samples." (PMID 36765773, 2023). "This is of great clinical significance given the emergence of drug resistance as a significant problem in the treatment of BRAF-mutated melanomas." (PMID 37760480, 2023). "The inhibition of epigenetic regulators to improve the treatment of BRAF-mutated melanoma has also been investigated in previous works." (PMID 36768289, 2023).
melanoma (continued). "BRAF(V600E) is the most prevalent mutation in melanoma, regulating tumor growth, invasion, and metastasis." (PMID 37760480, 2023). "Such melanomas are less likely to have a BRAF mutation (when present, they more frequently harbour a V600K than a V600E mutation) and have significantly higher mutation burden." (PMID 36765773, 2023). "BRAF-mutated melanomas display unique features: they tend to be more aggressive than BRAF wild-type (WT) melanomas, are more likely to metastasize to the brain, and are associated with shorter survival in patients with stage IV tumours." (PMID 37627054, 2023). "There is extensive experience with treatment of melanomas containing BRAF V600E somatic mutations using small molecule BRAF ± MEK inhibitors." (PMID 37444637, 2023). "Our data were not sufficient to validate these findings, as the mutational status was available for only 105 melanomas (BRAF mutant: 44, BRAF wildtype: 61)." (PMID 38201430, 2023). "In melanoma patients, especially BRAF-mutated melanoma patients, clinical studies showed a positive correlation between increased CYTL1 expression and shorter overall survival (OS) and disease-free survival (DFS)." (PMID 37745303, 2023). "Although the underpowered sample size limited statistical analysis, samples from non-responders had higher copy number variations and mutations in melanoma driver genes compared to responders in the BRAF V600+ subset." (PMID 36901733, 2023). "Trametinib, an oral MEK1 and MEK2 inhibitor, has been approved by the FDA in 2014 for BRAF V600 mutated melanoma treatment in a combination with the BRAF inhibitor dabrafenib." (PMID 37190302, 2023). "The BRAF(V600E)-activating mutation is present in approximately 50% of human melanomas and represents a major target for melanoma therapy." (PMID 37445731, 2023). "Only serum CXCL10 levels exhibited significant differences across patients harboring melanomas with different mutations (BRAF, CDKN2A, NF, NRAS)." (PMID 37435077, 2023). "Immunoblots showed a concentration-dependent increase of the cleaved PARP1 band and a concomitant decrease of its full-length band, in all BRAF-mutated melanoma cell lines." (PMID 36674794, 2023). "BRAF mutated melanomas with a high tumor mutation burden have a great chance to benefit from adjuvant anti-PD-1 therapy." (PMID 35192052, 2023). "In this context, non-steroidal anti-inflammatory drugs (NSAIDs)—commonly used as COX inhibitors—have been proposed as VMR-sensitisers in BRAF-mutated melanoma." (PMID 37198319, 2023). "The activation of kinases ERK1/2 and AKT is very important for allowing a high rate of cell proliferation, especially in BRAF-mutated melanoma cells." (PMID 36674794, 2023). "Consistent with the bimolecular significance of BRAF protein and its V600E mutation in carcinogenesis, several drugs targeting BRAF V600E mutations have been approved or under development to treat melanoma, ovarian cancer, thyroid cancer and colorectal cancer." (PMID 36759818, 2023). "Melanoma BM were included in 28 (16.6%) trials, four of them specifically for BRAF mutated melanoma." (PMID 37016421, 2023). "Prospective data and biomarkers are needed to further assess this option, which is being investigated in the phase III COLUMBUS-AD trial of adjuvant encorafenib and binimetinib in high-risk stage II melanoma with a BRAF mutation." (PMID 37072748, 2023). "Loss of PTEN function has been detected in about 10-30% of melanomas, most frequently in BRAF-mutated tumors." (PMID 38022574, 2023). "In vitro studies of BRAF-mutated melanoma have supported the role of MF-438 as a promising therapeutic target, especially when used in combination with MAPK inhibitors." (PMID 37700339, 2023).
melanoma (continued). "This article reports current evidence on the efficacy and safety of sequential immunotherapy with targeted therapy in patients with BRAF-mutated melanoma." (PMID 36995534, 2023). "Authors also found that the development of resistance obtained through EVs carrying PDGFRβ was not just a prerogative of the cell line LM-MEL-64, but also of another melanoma cell line (M229AR) after the exposure to BRAF-inhibitors and linked to resistance." (PMID 36831417, 2023). "In this study, we identified enriched pathways and DEGs associated with OS in BRAF-mutant melanoma via RNA sequencing and analysis of clinical survival data from melanoma samples." (PMID 37205993, 2023). "There has been growing acknowledgment of the widespread presence of v-rafmurine sarcoma viral oncogene homolog B (BRAF) mutational heterogeneity in melanoma within academic circles." (PMID 37959729, 2023). "In the BRIM-8 trial, patients with radically resected melanoma and BRAF V600 mutation were randomized to receive double-blind vemurafenib (BRAF inhibitor) 960 mg ×2 daily or placebo for 12 months." (PMID 37888038, 2023). "By knocking down CYTL1 in BRAF-mutated melanoma cells, we found that CYTL1 has a negligible effect on melanoma cell proliferation but affects melanoma invasion and metastasis." (PMID 37745303, 2023). "NRAS mutations in melanoma promote RAS-MEK signaling cascade by switching their signaling from BRAF to CRAF, facilitated by the disruption of the cAMP-PKA inhibitory pathway on CRAF activity." (PMID 38111008, 2023). "TERT promoter mutations are the most frequent mutations in melanoma, co-occur regularly with BRAF alterations and are associated with a poorer prognosis." (PMID 37296851, 2023). "In a pathological context, BRAF mutant melanomas demonstrate ‘oncogene addiction’ to the mutation and a relative paucity of other oncogenic mutations." (PMID 36539575, 2023). "We investigated the effects of HPF in three BRAF-mutated melanoma cell lines and observed a decrease in the expression level of glutathione peroxidase-4 (GPX-4)." (PMID 37507910, 2023). "A 72-year-old male patient was diagnosed with BRAF V600E-mutated melanoma with metastases in the liver, lymph nodes, lungs, pancreas, and stomach." (PMID 36865793, 2023). "For RAF, especially BRAF mutations have been more commonly identified in melanomas and other malignancies." (PMID 38239196, 2023). "In this context, lovastatin, a β-Hydroxy β-methylglutaryl-coenzyme A reductase (HMGCR) inhibitor, was shown to induce apoptosis in several BRAF-mutated and metastases-derived melanoma cell lines." (PMID 37495601, 2023). "This led to the randomized phase 3 trial where dabrafenib and trametinib regimen was compared against dabrafenib in advanced melanoma with BRAF V600E or V600K mutation." (PMID 36801912, 2023). "The effects of SCH772984/S63845 were comparable to those of vemurafenib/S63845 in BRAF-mutated melanoma cell lines." (PMID 36902392, 2023). "Tumor samples from 48 patients with advanced BRAF-mutated melanoma were collected before treatment and analyzed for TERT promoter mutation status." (PMID 37296851, 2023). "- All patients with metastatic or unresectable melanoma or those at high risk of relapse should be screened for BRAF V600 mutations, preferably in a metastatic lesion, and for adjuvant therapy in the primary tumor to guide therapeutic decision making." (PMID 36998456, 2023). "BRAF inhibitors are commonly used for melanoma patients whose tumors have BRAF mutations; however, most patients eventually acquire drug resistance." (PMID 37779896, 2023). "Based on the efficacy of BRAF inhibitors in melanoma patients, the same drugs approved for BRAF-mutated melanoma treatment were administered to BRAF-mutated NSCLC patients." (PMID 37111737, 2023). "The V600E mutation is the most frequent BRAF mutation and is observed in ~90% of melanomas that carry this mutation." (PMID 36678596, 2023).
melanoma (continued). "As an oncogenic driver in melanoma, BRAF mutation can be used as a target for precision therapy of CM32,33." (PMID 38155221, 2023). "The BRAF V600 mutation is present in 40-50% of metastatic melanomas and leads to activation of MAPK and ERK pathways." (PMID 38022574, 2023). "Examples of MAPK signaling altering metabolic function include the association between BRAF mutations and increased ketogenesis in melanoma, as well as the association between RAS-mutations and central carbon metabolism in pancreatic cancer." (PMID 37408209, 2023). "The functional loss of the tumor suppressor PTEN leading to AKT activation occurs in a large proportion of melanomas, and frequently co-occurs with oncogenic BRAF mutations." (PMID 37894325, 2023). "Melanoma is the deadliest form of skin cancer, with the BRAF(V600E) mutation being the most prevalent driver mutation." (PMID 37760480, 2023). "In this way, G18.EE-n-BuOH was fractioned to separate its components in subfractions according to their polarity, and the cytotoxic effect of the obtained subfractions was assessed in A375—a BRAF-mutated melanoma cell line." (PMID 37049869, 2023). "The case presented concerns a 41-year-old patient with locally advanced melanoma, being positive in mutation BRAF V600." (PMID 37241207, 2023). "Along with a MAPK pathway hyperactivation, BRAF-mutated melanoma cells exhibit increased RSK activity and can be effectively targeted by RSK inhibition particularly in the case of MAPK pathway inhibitor resistance." (PMID 37464364, 2023). "An activating missense mutation in codon 600 of exon 15 (V600E) of the BRAF gene has been identified in various tumor types, and BRAF inhibitors have yielded clinical benefits for patients with BRAF V600E-mutated cancers, especially melanoma and NSCLC." (PMID 37422534, 2023). "In conclusion, innate and acquired resistance to MAPK-targeted agents in BRAF-mutated melanomas and poor therapeutic options in the other subtypes make the identification of new targets highly important." (PMID 37508519, 2023). "BRAF mutational status was known in 56 out of 69 melanoma patients, in particular: 24 patients (42.85%) had BRAF-mutated melanoma while 32 patients (57.14%) were wild-type for BRAF." (PMID 37170241, 2023). "Melanomas with an atypical BRAF mutation encompass a diverse genetic alteration and are often subdivided into V600 and non-V600 mutants." (PMID 37370834, 2023). "This is the case of BRAF mutations in melanoma cells correlating with enhanced levels of immunosuppressive mediators such as IL-6 and IL-10 or anti-apoptotic Bcl-2 and Bcl-xL proteins, regulating the expression of several interleukins, such as IL-8 and IL-1β." (PMID 36768978, 2023). "Specifically, the antitumor activity of phenformin has been demonstrated in melanomas containing the v-Raf murine sarcoma viral oncogene homolog B1 (BRAF) activating mutation." (PMID 38132178, 2023). "BRAF V600E mutations are commonly found in melanoma and lung, thyroid, and colorectal cancers, as well as gliomas and acute leukaemias." (PMID 37240418, 2023). "Vemurafenib demonstrated safety and efficacy in both treatment-free and pre-treated BRAF-mutated melanoma patients." (PMID 36844227, 2023). "Our index does not contain molecular data such as EGFR mutation status in lung cancer patients, HER2 status in breast cancer patients and BRAF mutation status in melanoma patients." (PMID 37370784, 2023). "This review discusses the unmet needs of patients with BRAF-mutated melanoma in LA, including molecular testing strategies for detecting the mutation and their appropriate use within the regional context." (PMID 36998456, 2023).